DEUP1 (deuterosome assembly protein 1)
Description:
Key structural component of the deuterosome, a structure that promotes de novo centriole amplification in multiciliated cells. Deuterosome-mediated centriole amplification occurs in terminally differentiated multiciliated cells and can generate more than 100 centrioles. Probably sufficient for the specification and formation of the deuterosome inner core. Interacts with CEP152 and recruits PLK4 to activate centriole biogenesis (By similarity).
Synonyms: CCDC67; FLJ25393
Tractability: No criterion of Open Targets' tractability assessment is met for any kind of drug.
Gene: Protein-coding gene on chromosome 11 (93,329,971 to 93,438,487, forward strand). Ensembl gene ENSG00000165325.
Subcellular location: Cytoplasm
Gene Ontology:
Molecular function: identical protein binding; protein binding
Biological process: centriole replication; de novo centriole assembly involved in multi-ciliated epithelial cell differentiation; multi-ciliated epithelial cell differentiation
Cellular component: centriole; deuterosome; cytoplasm
Genetic constraint (gnomAD): Loss-of-function variants: 36 observed, 44.01 expected, observed/expected ratio (o/e) 0.82, 90% interval 0.63 to 1.08. The upper end of that interval is the gene's LOEUF score, 1.08, which puts it in group 4 of 6, group 1 being the genes least tolerant of losing a copy. Missense variants: 378 observed, 381.33 expected, observed/expected ratio (o/e) 0.99, 90% interval 0.91 to 1.08. Synonymous variants: 120 observed, 126.21 expected, observed/expected ratio (o/e) 0.95, 90% interval 0.82 to 1.11.
Homologues: Orthologues: chimpanzee DEUP1 (98% identical), macaque DEUP1 (96% identical), rabbit DEUP1 (89% identical), pig DEUP1 (88% identical), guinea pig DEUP1 (86% identical), dog DEUP1 (82% identical), rat Deup1 (81% identical), mouse Deup1 (80% identical), tropical clawed frog deup1 (33% identical). Paralogues in human: CEP63 (31% identical), CCDC18 (17% identical).
Diseases named in the same sentence as DEUP1 in open-access papers:
DEUP1 is named in the same sentence as 15 diseases in open-access papers, as found by Europe PMC text mining. Sharing a sentence is not in itself a finding about the gene and the disease. The quoted sentences say what the papers report.
Alstrom syndrome (1 paper, 2021). A multisystemic disorder characterized by cone-rod dystrophy, hearing loss, obesity, insulin resistance and hyperinsulinemia, type 2 diabetes mellitus, dilated cardiomyopathy (DCM), and progressive hepatic and renal dysfunction. "While the exact role of Deup1 in the retina has not been determined, defects in primary cilium function in photoreceptors and the RPE leads to retinal degeneration as part of several syndromic ciliopathies like Bardet-Beidl syndrome and Alstrom syndrome." (PMID 34440888, 2021).
DEUP1 also shares sentences with these, for which no sentence is quoted: cancer (4 papers); prostate carcinoma (4); tumor (4); hepatocellular carcinoma (3); gastric cancer (2); cannabis dependence (1); ciliopathies (1); glioblastoma multiforme (1); lung carcinoma (1); lymph node metastasis (1); Nephroblastoma (1); papillary thyroid carcinoma (1); retinal degeneration (1); thyroid cancer (1).